IL11 (interleukin 11)
Diseases named in the same sentence as IL11 in open-access papers (continued):
Sharing a sentence is not in itself a finding about the gene and the disease.
skin cancer (3 papers, 2016 to 2025). "We identify that the same inflammatory myofibroblast phenotype (IL11+MMP1+CXCL8+IL7R+) can be observed in early human skin wounds, skin cancer and inflammatory skin diseases with scarring risk." (PMID 40993240, 2025). "There are only limited studies on the involvement of the other IL-6 family cytokines in skin cancer, though we now know that IL-11 is over-expressed in skin tumors and promotes tumor development through the activation of STAT3." (PMID 31051015, 2016). "In addition to IL-22, IL-6 and IL-11 also drives the malignant progression of skin cancer cells through the activation of STAT3 and upregulation of inflammatory and angiogenic factors." (PMID 31051015, 2016).
Thyroid-Associated Ophthalmopathy (3 papers, 2022 to 2025). "Transforming growth factor β1 (TGFβ1)-interleukin 11 (IL11) is a newly found critical signaling pathway in fibrotic diseases such as Graves’ orbitopathy (GO)." (PMID 40018034, 2025).
acute megakaryocytic leukemia (2 papers, 2015 to 2023). "have reported a case of acute megakaryocytic leukemia with osteosclerosis showing that interleukin 11, a factor derived from leukemic cells, induced the expression of osteoprotegerin in osteoblast MG63 cells in vitro." (PMID 37206285, 2023). "It was reported that interleukin-11 (IL-11), which is secreted from blasts, acts as an osteoprotegerin (OPG) inducing factor in patients with acute megakaryocytic leukemia and may lead to osteosclerosis." (PMID 26694466, 2015).
acute myeloid leukemia (2 papers, 2021 to 2023). Acute myeloid leukemia (AML) is a group of neoplasms arising from precursor cells committed to the myeloid cell-line differentiation. "In acute myeloid leukemia (AML) and CML, blocking IL-1 signaling (for example, with anti-IL-1RA or anti-IL1RAP antibodies, IRAK1/4 inhibitors, IL-11/4 inhibitors, AP antibodies) eliminates LSCs in the TME, thereby preventing recurrence in patients." (PMID 36761742, 2023). "The YTHDF2 encoding gene was found to be overexpressed and responsible for development of acute myeloid leukemia (AML), whereas it turned into a tumor suppressor by targeting EGFR, IL11 and SERPINE2 mRNAs for degradation in hepatocellular carcinoma." (PMID 33658012, 2021).
adenomyosis (2 papers, 2024 to 2025). The growth of endometrial tissue inside the muscular wall of the uterine corpus. "IL-11 plays a crucial role in regulating trophoblastic invasion, and adenomyosis is associated with decreased levels of IL-11, which can lead to early pregnancy loss." (PMID 39795558, 2024). "Importantly, administering IL-11 improved these conditions, highlighting its potential as a therapeutic intervention for the fertility challenges in adenomyosis." (PMID 39794729, 2025). "Transcriptome sequencing, dual-luciferase reporter assays, and chromatin immunoprecipitation (ChIP) experiments showed that LEF1 could bind to the promoter region of interleukin (IL)-11 and promote its transcription, and IL-11 expression was also found to be downregulated in adenomyosis patients." (PMID 39794729, 2025).
Alport syndrome (2 papers, 2023). A rare renal disease characterized by glomerular nephropathy with hematuria progressing to end-stage renal disease (ESRD), frequently associated with sensorineural deafness, and occasionally with ocular anomalies. "We previously examined the role of IL-11 in kidney disease in a mouse model of Alport syndrome, which is a disease of the renal glomerulus caused by mutation in collagen type IV." (PMID 37816442, 2023). "IL-11:EGFP reporter mice were crossed to Alport syndrome mice (129-Col4a3tm1Dec/J or Col4a3−/−), which resulted in specific up-regulation of IL-11 in RTECs that was accompanied by increased SNAI1 expression." (PMID 37816442, 2023).
Alzheimer disease (2 papers, 2021 to 2023). A progressive, neurodegenerative disease characterized by loss of function and death of nerve cells in several areas of the brain leading to loss of cognitive function such as memory and language. "Some cytokines seemed more specific to cognitive aspects of the pathology as they were found deregulated in Alzheimer’s disease (AD) and FTD patients such as IL-11, IL-15, and IL-12." (PMID 34970118, 2021).
astrocytoma (2 papers, 2015 to 2023). "As an underlying mechanism, it was found that in high‐grade astrocytoma, mainly GBM, interleukin 11 (IL‐11) secreted by microglia activates STAT3‐MYC signaling." (PMID 36776000, 2023). "The induction of LIF, IL11, and HBEGF mRNA in human astrocytes by FTY-P was confirmed in independent experiments on primary astrocytes and human astrocytoma cells by qPCR." (PMID 26419927, 2015).
cardiac hypertrophy (2 papers, 2019 to 2024). "Since IL-11 is a member of the IL-6 family, we infer that IL-11 can also cause elevated BNP via the cardiac hypertrophy pathway." (PMID 30877597, 2019).
cerebral palsy (2 papers, 2019 to 2024). A group of disorders affecting the development of movement and posture, often accompanied by disturbances of sensation, perception, cognition, and behavior. "Also, increased levels of IL6, IL11, andIL13 have been reported in dried blood samples of infants with cerebral palsy.The results of an animal study showed that the serial injection of synthetic IL6prevents learning disabilities and delays the loss of neurons." (PMID 31435616, 2019).
chronic atrophic gastritis (2 papers, 2022 to 2025). Atrophic gastritis that is persistent and long-standing. "Median LIF expression was significantly higher at 1.68 pg/mL in GC patients versus 0.55 pg/mL in gastritis patients, while IL‐11 expression was 0.63 pg/mL in GC patients compared to 0.14 pg/mL in gastritis patients." (PMID 41163398, 2025). "H. pylori load, LIF, and IL‐11 were significantly higher in GC patients than in gastritis patients." (PMID 41163398, 2025).
chronic endometritis (2 papers, 2020 to 2024). A non-granulomatous or granulomatous chronic inflammation of the endometrium. "For instance, chronic endometritis is characterized by a modified gene expression profile involving proinflammatory mediators like IL11, IL17, TGF-β, CCL4, IGFBP1, and CASP8, contrasting with the gene expression profile observed in normal fertile women during the implantation window." (PMID 38927030, 2024).
chronic lung disease (2 papers, 2020 to 2022). According to the definitions of the American and British Thoracic Societies, including pulmonary functional tests, X-rays, and CT scans for items such as fibrosis, bronchiectasis, bullae, emphysema, nodular or lymphomatous abnormalities. "While IL-11 was initially implicated in pulmonary viral and inflammatory diseases, more recent studies have shown strong evidence that IL-11 is elevated in chronic lung diseases that have a fibrotic component." (PMID 33262481, 2020). "Using control, IPF and IPF with PH lungs from human and PH animal models, we showed for the first time that IL-11/IL-11Rα may be implicated in the development of PH associated to IPF chronic lung disease." (PMID 36376885, 2022).
chronic obstructive pulmonary disease (2 papers, 2020 to 2022). A chronic and progressive lung disorder characterized by the loss of elasticity of the bronchial tree and the air sacs, destruction of the air sacs wall, thickening of the bronchial wall, and mucous accumulation in the bronchial tree. "This study demonstrated that BALF IL11 expression was largely restricted to patients with LUAD, with or without chronic obstructive pulmonary disease (COPD)." (PMID 35883698, 2022).
Cirrhosis (2 papers, 2009 to 2024). A chronic disorder of the liver in which liver tissue becomes scarred and is partially replaced by regenerative nodules and fibrotic tissue resulting in loss of liver function. "A possible explanation is that other factors, such as suppressive effects of viruses on bone marrow and antibody-mediated destruction of platelets, may play a more important role in HBV-related cirrhosis than that in alcohol cirrhosis, in addition to decreased thrombopoeitin and interleukin-11." (PMID 19196464, 2009).
clear cell renal carcinoma (2 papers, 2016 to 2019). A malignant epithelial neoplasm of the kidney characterized by the presence of lipid-containing clear cells within a vascular network. "KRT8 upregulated expression can promote the metastasis of clear cell renal cell carcinoma (ccRCC) cells by up-regulating IL-11 expression, inducing IL-11 autocrine, and initiating the STAT3 signaling pathway." (PMID 30634629, 2019).
demyelinating disease (2 papers, 2013 to 2014). A broad group of disorders that affect the myelin sheaths that cover the neurons. "More recently, it was shown that overexpression of IL-11 in the brain reduces the extent of demyelination and enhances remyelination in the cuprizone-induced demyelinating disease model." (PMID 25078447, 2014). "Overall, we demonstrate that IL-11 is of therapeutic interest for MS and other demyelinating diseases by limiting demyelination and promoting remyelination." (PMID 23818742, 2013).
demyelination (2 papers, 2013 to 2014). "In this study, the cuprizone-induced demyelination mouse model was used to elucidate effects of IL-11 on de- and remyelination, independent of the immune response." (PMID 23818742, 2013). "Future studies should evaluate whether the IVIg-induction of IL-11 has a consequence on myelination and repair in a non-autoimmune-based demyelination/remyelination model." (PMID 25078447, 2014).
dissection (2 papers, 2020 to 2023). The separation and isolation of tissues for surgical purposes, or for the analysis or study of their structures. "In animal model studies involving overexpression or inhibition of IL-11, IL-11 is involved in the development of aortic dissection by inducing phenotype transformation of vascular smooth muscle and aortic vascular remodeling." (PMID 37304948, 2023). "This limited evidence supports the role of IL-11, IL-22, IL-17, and IL-3 in aortic dissection; however, further investigations are needed to determine whether these interleukins have a role in the early stages of TAA development." (PMID 33081376, 2020).
E. coli infection (2 papers, 2019 to 2023). "Therefore, we also investigated the transcriptional changes in interleukin-family genes and found that E. coli infection significantly increased the expressions of IL-1α, IL-11, NFIL-3, IL-16, and other cytokines." (PMID 36876070, 2023).
endometrial adenocarcinoma (2 papers, 2012 to 2025). "Another study highlighted a novel mechanism regulating IL-11 expression in endometrial adenocarcinoma cells via a prostaglandin receptor and calcineurin-1." (PMID 40564925, 2025). "It has been reported that IL-8 and IL-11 are induced by the CN/NFAT signaling pathway in prokineticin 1 receptor (PROKR1)- and prostanoid F receptor-expressing Ishikawa (human endometrial adenocarcinoma) cells." (PMID 22662209, 2012).
endometrial tumour (2 papers, 2010 to 2017). "Exogenous IL11 promoted AN3CA subcutaneous xenograft endometrial tumour growth in vivo andIL11Rα inhibition and doxorubicin combinantation treatment enhanced apoptosis in AN3CA cells in vitro and impaired high grade endometrial tumourigenesis in vivo." (PMID 28186993, 2017). "IL11 protein and mRNA, along with IL11Rα protein levels are progressively increased with increased endometrial tumour grade, which is in line with findings in other tumour types such as ovarian and colorectal." (PMID 28186993, 2017). "It is well known that IL11 has an anti-apoptotic role and here we demonstrated that IL11 signalling blockade induced apoptosis in endometrial tumour xenografts." (PMID 28186993, 2017). "IL11 immunostaining was significantly elevated in the endometrial tumour epithelial cells from Grade 1 and 3 compared to endometrial epithelium from postmenopausal and cycling women." (PMID 20553623, 2010). "We hypothesized that miR-1 regulates IL11 in endometrial tumours and that IL11 promotes high grade endometrial tumour growth." (PMID 28186993, 2017). "In conclusion, IL11 has comprehensively emerged as an important factor stimulating epithelial endometrial tumour progression and IL11Rα inhibition may offer a new strategy for novel therapeutic development." (PMID 28186993, 2017). "In this report, we hypothesized that micro-RNA(miR)-1 regulates IL11 and that IL11 promotes high grade endometrial tumour growth." (PMID 28186993, 2017).
experimental autoimmune encephalomyelitis (2 papers, 2013 to 2014). An autoimmune demyelinating disease of the central nervous system that is produced experimentally in animals by the injection of homogenized brain or spinal cord in Freund's adjuvant. "Both IVIg and IL-11 have been shown to ameliorate experimental autoimmune encephalomyelitis (EAE), an animal model of MS." (PMID 25078447, 2014). "Systemic IL-11 treatment was shown to ameliorate clinical symptoms in experimental autoimmune encephalomyelitis (EAE), an animal model of MS." (PMID 23818742, 2013).
glomerulonephritis (2 papers, 2019 to 2021). A renal disorder characterized by damage in the glomeruli. "For example, IL-11 treatment decreases glomerular nuclear factor “kappa-light-chain-enhancer” (NF-kappa) activity and reduces renal injury in experimental glomerulonephritis." (PMID 34205404, 2021). "Interestingly, studies using a rat model of glomerulonephritis demonstrated that administration of IL-11 could reduce the glomerular necrosis and proteinuria associated with the disease." (PMID 30871285, 2019). "Further research using murine models of glomerulonephritis identified NF-Kappa B activity and TGF-β expression as key components involved in the reduction of renal injury due to IL-11 treatment." (PMID 30871285, 2019).
HCMV infection (2 papers, 2018 to 2022). "Here, we report that hCMV infection strongly induces EC IL-11, and document its temporal expression dynamics compared to the induction of IL-6." (PMID 29807687, 2018). "The finding that EC can produce IL-11 in response to hCMV infection, has significance from the perspective of both EC biology and viral pathogenesis." (PMID 29807687, 2018). "We detail temporal EC IL-11 translation and protein secretion dynamics in response to hCMV infection, and reveal distinct differences compared to EC IL-6." (PMID 29807687, 2018). "We found that TOs secreted relatively few cytokines in response to HCMV infection, including pentraxin-3 (PTX3), first described as an endothelial factor induced by IL-1β treatment, IL-8, and IL-11." (PMID 35975985, 2022).
head and neck squamous cell carcinoma (2 papers, 2025). A squamous cell carcinoma that arises from any of the following anatomic sites: lip and oral cavity, nasal cavity, paranasal sinuses, pharynx, larynx, and salivary glands. "In head and neck squamous cell carcinoma, interleukin-11 (IL-11) was identified as a downstream target of histone lactylation at lysine 9 of histone H3 (H3K9la)." (PMID 40057816, 2025).
hyperlipidemia (2 papers, 2021 to 2023). "No significant influence of hyperlipidemia was found on other second-line therapies, including decitabine, rituximab, vindesin, splenectomy, danazol, Cyclosporin A, and IL-11." (PMID 37784127, 2023). "Interestingly, inhibition of IL-11 reduced the collagen content of uninjured carotid arteries as compared to either IgG or buffer control mice, showing an additional effect on hyperlipidemia-induced arterial remodeling in the absence of mechanical injury." (PMID 34667238, 2021).
hypersplenia (2 papers, 2011). "Both patients had hypersplenia and elevated levels of ALT and AST, and it seemed likely that these findings were due to the side effects of a drug, such as IL-11, after RFA therapy." (PMID 21619578, 2011).
injury (2 papers, 2020 to 2025). Damage inflicted on the body as the direct or indirect result of an external force, with or without disruption of structural continuity. "Widjaja and colleagues also reveal that IL-11 induces mitochondrial dysfunction in acetaminophen-evoked liver injury." (PMID 40092733, 2025). "UCHL-1 and IL-11 are not useful markers in the case of mild head trauma because their concentrations did not change in comparison to the control group." (PMID 32987792, 2020). "In contrast to these results, we did not observe significant changes in IL-11 concentration as a consequence of mild head trauma." (PMID 32987792, 2020).
Insulin resistance (2 papers, 2022 to 2023). Increased resistance towards insulin, that is, diminished effectiveness of insulin in reducing blood glucose levels. "Fasting level and AUC of serum insulin in oGTT as well as homeostasis model assessment of insulin resistance (HOMA-IR) were higher in IL-11−/− mice." (PMID 36424386, 2022).
intestinal tumor (2 papers, 2019 to 2021). "Regulation of IL-11 by the β-catenin pathway has not been reported in fibrosis, however, cooperation of TGF-β and WNT in regulating IL-11 was observed in intestinal tumor models." (PMID 34576234, 2021). "However, given that conventional IL11 signaling and IL6 trans‐signaling both facilitate the growth of intestinal tumors, our observations do not address the relative contribution by which the bazedoxifene effect is mediated through inhibition of each of these mechanisms." (PMID 30885958, 2019).
ischemic disease (2 papers, 2022 to 2023). Lack of blood supply to an area of the body, resulting in impairment of tissue oxygenation. "We found that OGD may affect the IDO1/KYN metabolic pathway through IL11, thereby affecting fibroblast senescence and collagen expression, which may provide an effective basis for the treatment of cellular senescence caused by ischemic disease." (PMID 36292942, 2022). "In ischemic diseases, the administration of IL-11 improves blood supply." (PMID 37304948, 2023). "In endothelial cells, IL-11 primarily promotes angiogenesis, thus ameliorating ischemic disease." (PMID 37304948, 2023).
joint diseases (2 papers, 2018 to 2023). "Based on the analysis, we further found one OA case with high IL-6 and low IL-11 levels (10731 ng/ml IL-6 vs. 1255 ng/ml IL-11) in the synovial fluid of the right knee associated with recurrent joint effusion and progressive OA joint damage." (PMID 30197757, 2018). "The hematopoietic effects of IL-11 can be used clinically to treat bone and joint diseases." (PMID 38352248, 2023).
malaria (2 papers, 2021 to 2025). Malaria is a serious and sometimes fatal disease caused by a parasite that commonly infects a certain type of mosquito which feeds on humans. "Our studies showed that co-incubation of brain ECs with plasma from malaria patients resulted in significantly increased secretion of IL-11, CXCL5, CXCL10, VEGF and angiopoietin-like protein 4 (ANGPTL4)." (PMID 34359826, 2021). "Stimulation of ECs with plasma from malaria patients resulted in significantly increased levels of IL-11, CXCL5, CXCL8, CXCL10 and VEGF in comparison to stimulation of ECs using plasma from healthy controls." (PMID 34359826, 2021). "Culturing ECs with plasma from malaria patients (27 returning travellers) resulted in significantly increased secretion of IL-11, CXCL5, CXCL8, CXCL10, vascular endothelial growth factor (VEGF) and angiopoietin-like protein 4 (ANGPTL4) if compared to matching controls (22 healthy individuals)." (PMID 34359826, 2021). "For cytokines IL-6, IL-1RA, IL-10 and IL-11 and chemokines CXCL1, CXCL8, CXCL10, CCL3 and CCL2, significantly higher concentrations were found in plasma samples of malaria patients compared to healthy controls." (PMID 34359826, 2021). "In response to blood-stage malaria, Il11 expression took a two-peak course that was not significantly different between unvaccinated and vaccinated mice." (PMID 40243929, 2025). "A decrease in expression, albeit non-significant, after stimulation with plasma from malaria patients compared to the controls was observed for il11 expression (p = 0.05), which is in contrast to the LEGENDplex results." (PMID 34359826, 2021).